CLOCK (clock circadian regulator)
Diseases named in the same sentence as CLOCK in open-access papers (continued):
Sharing a sentence is not in itself a finding about the gene and the disease.
hepatocellular carcinoma (19 papers, 2011 to 2024). A malignant tumor that arises from hepatocytes. "The impact of clock associated lncRNAs in hepatocellular carcinoma showed that the lncRNA HULC upregulates the expression levels of CLOCK and its downstream targets, like PER1 and CRY1 in hepatoma cells in vivo." (PMID 32344623, 2020). "Additionally, CLOCK has been linked with a worse prognosis for hepatocellular carcinoma." (PMID 37373286, 2023). "In a hepatoma cell line, noc expression is controlled by the binding of the CLOCK/BMAL1 heterodimer to an E-box element of the noc promoter, similarly to the activation of other clock-controlled genes." (PMID 38203224, 2023). "Recently, it was shown that HULC functions as an oncogene in hepatoma cells, acting mechanistically by promoting lipogenesis and disturbing the Clock circadian regulator (CLOCK)/brain and muscle arnt-like protein-1 (BMAL1) complex." (PMID 26887054, 2016). "Additionally, BMAL1 and CLOCK can impact the cell cycle of hepatocellular carcinoma cells by regulating the expression of Wee1 and P21, thereby contributing to tumor progression." (PMID 38703241, 2024). "Hepatocellular Carcinoma Up-regulated Long Non-coding RNA (HULC) and Clock circadian regulator (CLOCK) mRNA 5′-UTR have a complementary base paring region, and the results of luciferase reporter gene assays suggest that HULC can improve the stability of CLOCK mRNA." (PMID 31097003, 2019).
colorectal cancer (17 papers, 2013 to 2024). A primary or metastatic malignant neoplasm that affects the colon or rectum. "For example, compared to healthy tissue, colorectal cancers (CRC) often display higher CLOCK or BMAL1 expression, which is associated with liver metastasis and poorly differentiated or late-stage CRC cancer." (PMID 32388500, 2020). "The CLOCK gene itself is mutated in 53% of colorectal cancer samples." (PMID 33089179, 2019). "For example, overexpression of CLOCK in human colorectal carcinoma cell lines correlates with increased expression of angiogenesis-related genes such as HIF-1α, ARNT and VEGF, with CLOCK knockdown showing the opposite results." (PMID 38173841, 2023). "Angiogenic factor expression in TME decreases when CLOCK shRNA is knocked down and increases when CLOCK is overexpressed in colorectal cancer cells, according to genetic studies." (PMID 36685904, 2022). "In colorectal cancer, the transcriptional levels of CLOCK, CRY1, and NR1D1 were upregulated in 1, 1, and 2 datasets, respectively." (PMID 35116071, 2022). "For instance, CLOCK expression levels increased significantly in human colorectal cancer (CRC) tissues, which are closely related to late TNM staging and positive lymph node metastasis." (PMID 34977153, 2021). "In this study, for the first time, three functional polymorphisms in the CLOCK sequence, and five miRNAs regulating CLOCK, BMAL1 and PERIOD in advanced colorectal cancer patients and their effect on survival were analyzed." (PMID 27666868, 2016). "For example, the core circadian pathway members PER2 and BMAL1 serve as tumor suppressor in lung cancer, BMAL1 and CLOCK respectively act as tumor suppressor and oncogene in colorectal cancer, BMAL1 inhibits ferroptosis to increase the oncogenesis of acute myeloid leukemia." (PMID 38951864, 2024). "CLOCK knockout decreases angiogenesis factor expression in human colorectal cancer (CRC) cells, while CLOCK overexpression increases it." (PMID 38678017, 2024). "For instance, CLOCK or BMAL1 can act as a tumor suppressor in prostate, breast, ovarian, and pancreatic cancers, but they promote tumor growth in colorectal cancer and acute myeloid leukemia." (PMID 39001398, 2024).
type 2 diabetes (17 papers, 2013 to 2025). "The interaction between MTNR1A gene rs2119882 locus and CLOCK gene rs1801260 locus was associated with the risk of type 2 diabetes (RERI = 1.07, (95% CI, 0.23–1.91); AP = 0.77, (95% CI, 0.36–1.17))." (PMID 37138267, 2023). "For example, homozygous CLOCK mutant-obese mice exhibited hyperlipidemia, hepatic steatosis and hyperglycemia and insufficient compensatory insulin production (a hallmark of type 2 diabetes mellitus)." (PMID 34943809, 2021). "Specifically, in the present study, we established causality by inhibiting the action of the CLOCK/BMAL1 complex, having observed that leukocyte–endothelial interactions were enhanced in a similar way to that seen in type 2 diabetes participants." (PMID 38981930, 2024). "The purpose of this study is to investigate the association of rotating night shift work, CLOCK, MTNR1A, MTNR1B genes polymorphisms and their interactions with type 2 diabetes among steelworkers." (PMID 37138267, 2023). "Type II diabetes increases the protein level of liver rhythm molecule CLOCK and impairs the mitochondrial morphology, dynamics (OPA1 and Fis1), and mitophagy, which can be optimized by two differently timed exercises." (PMID 36012573, 2022). "In the same study evidence of a close link between the proper functioning of an islet-located circadian clock and the development of type 2 diabetes, after conditional knockout of CLOCK or BMAL1 in islets, was provided." (PMID 23535335, 2013). "Interestingly, inhibition of CLOCK/BMAL1 activity in leukocytes using the CLOCK inhibitor CLK8 mimicked the effects of type 2 diabetes on leukocyte–endothelial interactions." (PMID 38981930, 2024). "In addition, there is little epidemiological evidence about the interaction between CLOCK, MTNR1A, MTNR1B genes polymorphisms and shift work on type 2 diabetes." (PMID 37138267, 2023). "Few candidate gene studies reported associations of single nucleotide polymorphisms (SNPs) in CLOCK, ARNTL (encoding BMAL1), and PER2 with risk factors for the metabolic syndrome and type-2 diabetes, such as abdominal obesity, hypertension, fatty liver, and an atherogenic lipid profile." (PMID 26726810, 2016). "Thus, from the perspective of population epidemiology, this study aims to explore the association of rotating night shift work, CLOCK, MTNR1A, MTNR1B genes polymorphisms and their interactions with type 2 diabetes among steelworkers through a case–control study." (PMID 37138267, 2023). "At the molecular level in humans, a single nucleotide polymorphism in CLOCK is associated with abnormal fatty acid metabolism and development of fatty liver, and a polymorphism in the BMAL1 core circadian clock gene is associated with susceptibility to hypertension and type-2 diabetes." (PMID 25988133, 2015). "Participants with type 2 diabetes showed increased BMAL1 and NR1D1 mRNA levels and decreased protein levels of circadian locomotor output cycles kaput (CLOCK), cryptochrome 1 (CRY1), phosphorylated basic helix-loop-helix ARNT like 1 (p-BMAL1) and period circadian protein homologue 2 (PER2)." (PMID 38981930, 2024). "Moreover, there was a positive gene–gene interaction between CLOCK gene rs1801260 locus and MTNR1A gene rs2119882 locus on type 2 diabetes." (PMID 37138267, 2023).
mood disorder (14 papers, 2010 to 2025). A cognitive disorder a disturbance in which the person's mood is hypothesized to be the main underlying feature. "Moreover, alterations in CLOCK gene expression and thus changes in the dopaminergic, GABAergic, and glutamatergic systems are associated with known epilepsy comorbidities, such as mood disorders, ADHD, autism spectrum disorder, and schizophrenia." (PMID 40572688, 2025). "Variants in genes including PER3, CLOCK, and BMAL1 influence not only circadian phase preference but also cognitive performance patterns, mood disorder susceptibility, and drug metabolism." (PMID 41226802, 2025). "For their influence on brain development, genetic variations of circadian genes (e.g., CRY1, CLOCK, and NPAS2) are oftentimes associated psychiatric disorders such as anxiety, mood disorders, and alcohol use." (PMID 36833279, 2023). "For example, variants of circadian genes, such as CLOCK, BMAL1, NPAS2, Per3, and NR1D1, play a role in mood disorders, mainly based on statistical analyses." (PMID 35999325, 2022). "For example, Bunney and colleague showed that an altered circadian function and altered expression of the central circadian clock genes, BMAL1/CLOCK (Npas2) in mood disorders." (PMID 25408907, 2013). "Genetics studies have found associations with CLOCK, PER1-3, and CRY1, and Sirtuin genes in mood disorders." (PMID 21542937, 2011). "Recent study investigated the association between the six tagging SNPs including rs1801260 in CLOCK and schizophrenia and mood disorders in the Japanese population." (PMID 20704703, 2010). "The determination that CLOCK itself interacts with NF-κB to activate transcription at NF-κB responsive promoters further supports this as a candidate pathway for linking circadian mechanisms and mood disorders." (PMID 26379559, 2015). "Previous studies have demonstrated important associations of clock genes with sleep and mood disorders, as for example between PER2 variants and familial ASPS, between PER3 variants and diurnal preference and DSPS, and between CLOCK and mood disorders and human diurnal preference." (PMID 20174623, 2010).
Hypertension (13 papers, 2010 to 2025). The presence of chronic increased pressure in the systemic arterial system. "Among patients with essential hypertension in a Chinese population, carriers of the C allele in the CLOCK rs1801260 SNP were more susceptible to insulin resistance and were at greater risk of developing high night-time systolic blood pressure." (PMID 37761843, 2023). "ARNTL, rs3789327, was connected with T2DM in MI patients, while rs13124436 and rs6811520 of the CLOCK gene were connected with hypertension, T2DM, and systolic blood pressure in MI patients." (PMID 32050674, 2020). "Human studies have identified genetic variants and expression patterns of circadian clockgenes, such as ARNTL, CLOCK, CRY2,NPAS2 or PER2, that are associated with metabolicsyndrome, hypertension or diabetes mellitus type 2." (PMID 29767668, 2018). "Other studies have revealed associations between: polymorphisms in BMAL1 with hypertension and type 2 diabetes, hypertension and NPAS2 (CLOCK gene analogous), and glucose and PER2." (PMID 20712885, 2010).
Anxiety (12 papers, 2016 to 2025). Intense feelings of nervousness, tension, or panic often arise in response to interpersonal stresses. "The results at baseline indicated a significant association between CLOCK and state anxiety (χ2 = 20.020, p < 0.05), suggesting individuals with higher CLOCK expression levels were more likely to have lower levels of state anxiety." (PMID 41383341, 2025). "In addition, due to cross-communication between neurohormones, inflammatory pathways, and circadian gene expression, psychological disorders are closely related to each other; specifically, the CLOCK gene can directly affect anxiety symptoms." (PMID 41383341, 2025). "After 7 day of optical activation for 1 h per day, mice exhibited mania-like behaviors with less anxiety, which was similar to the behavior of CLOCKΔ19 mice 111, suggesting that CLOCK may regulate emotion by acting on the activity of dopaminergic VTA neurons." (PMID 37781027, 2023). "The disruption of CLOCK resulted in lower immobility in the forced swim test, a greater preference for rewarding stimuli, such as sucrose solution and cocaine, a lower threshold within intra-cranial self-stimulation at lower drug doses, lowered anxiety levels, and less depressive-like behavior." (PMID 29027157, 2017). "The rs934945 SNP might influence the interaction between PER2 and other clock genes (e.g., CLOCK, BMAL1), leading to dysregulation of the circadian network and increased susceptibility to sleep disorders when combined with psychological stressors like anxiety and depression." (PMID 40951374, 2025). "When using RNA interference to specific knock down the CLOCK in VTA, mice exhibited hyperactivity and decreased anxiety behavior resembling the CLOCKΔ19 mice." (PMID 37781027, 2023). "Moreover, CLOCK expression was positively correlated with ADRB2 expression, serum NE, anxiety state and cancer development in patients with lung cancer, suggesting CLOCK expression as a promising prognostic factor for chronic stress-related lung cancer." (PMID 39054537, 2024). "This hypothesis is supported by the fact that over-expression of CLOCK in the VTA reduces hyperactivity and restores anxiety-related behavior almost to wild-type level in the ClockΔ19 mutant mice." (PMID 29027157, 2017). "Thus, it would be interesting to examine other mood-like behaviors of Per1ldc/Per2ldc double mutant mice to determine if the opposing roles of CLOCK and PER only apply to anxiety-like behaviors." (PMID 29230328, 2017).
Hyperglycemia (12 papers, 2012 to 2025). An increased concentration of glucose in the blood. "In our previous work in the Genetics of Lipid Lowering Drugs and Diet Network (GOLDN) population, we observed that carriers of the minor allele (G) for the CLOCK-rs4580704 SNP presented lower weight, fasting-insulin and hyperglycemia risk." (PMID 26739996, 2016). "One randomized control trial assessing the impact of a Mediterranean diet, which are generally found to be anti-inflammatory, found that the maintenance of a Mediterranean diet had a protective effect against impacts of the CLOCK gene and increased hyperglycemia." (PMID 36678290, 2023). "The CLOCK gene is the master regulator of circadian rhythms and its disruption impairs metabolic homeostasis, leading to hyperlipedemia, hepatic steatosis, hyperglycemia, and hypoinsulinemia in mouse models." (PMID 38250971, 2023). "The signaling pathways that are directly triggered by hyperglycemia, probably through alterations in CLOCK genes and acetylation of GR or due to the hyperglycemia-induced production of ROS and oxidative stress may result in a GR resistant state." (PMID 34681832, 2021). "Based on above and bearing in mind that ROS, oxidation status and alterations in CLOCK genes impair GR function, one may propose the following model for the relationship between stress, hypercortisolism, hyperglycemia and GR resistance in immune and brain cells." (PMID 34681832, 2021). "Thus, it can be postulated that the effects of the CLOCK gene on glucose metabolism in the peripheral organs may be a mechanism involved in the development of hyperglycemia." (PMID 30728411, 2019).
insomnia (12 papers, 2011 to 2024). A sleep disorder characterized by difficulty in falling asleep and/or remaining asleep. "This suggests that gender-specific CLOCK gene variants not only influence sleep regulation and insomnia but also survival outcomes." (PMID 39594805, 2024). "In this longitudinal study, we observed a significantly modified insomnia risk associated with the CLOCK gene depending on food groups." (PMID 37242182, 2023). "For example, patients carrying the C allele of rs1801260 in CLOCK showed a high incidence of insomnia during paroxetine or fluvoxamine therapy." (PMID 36658428, 2023). "Specifically, males with the CLOCK rs12649507 GG homozygote showed a higher risk of developing insomnia than those with the A allele." (PMID 37242182, 2023). "In this longitudinal study, we observed significantly modified insomnia risks depending on the consumption of food groups associated with CLOCK rs12649507 and rs4580704 in 775 males and 655 females in the general population." (PMID 37242182, 2023). "CLOCK (Circadian Locomotor Output Cycles Kaput) is an important regulator of circadian rhythm, disruptions of which have been associated with pain, insomnia, insulin resistance, immunological function and impaired mitochondrial function." (PMID 37915075, 2023). "Our current findings of the mitigating effects of fruit intake on the insomnia risk associated with the CLOCK gene may be attributed to the abundance of antioxidants and vitamins in fruits." (PMID 37242182, 2023). "Hazard models were used to examine whether the consumption of certain food groups modified the risk of insomnia associated with CLOCK rs12649507 in males and females." (PMID 37242182, 2023). "Food intake could mitigate or exacerbate the risk for insomnia associated with the CLOCK gene." (PMID 37242182, 2023). "This study investigated the associations between the clock circadian regulator (CLOCK) polymorphisms rs12649507 and rs4580704 and the risk of insomnia, as well as its interactions with food groups." (PMID 37242182, 2023). "Antipsychotic-induced restless legs syndrome was linked to polymorphisms located on CLOCK, BTBD9, GNB3, and TH genes, clozapine-induced somnolence was correlated with polymorphisms of HNMT gene, while insomnia was associated with variants of the MTNR1 gene." (PMID 29587340, 2018). "Moreover, another study showed that climacteric females with CLOCK rs12649507 homozygous for TT had a 1.78 times higher likelihood of insomnia (95% confidence interval [CI]: 1.16−2.75)." (PMID 37242182, 2023). "The mechanisms underlying the interaction between food groups and the insomnia risks associated with CLOCK rs12649507 and rs4580704 were not completely elucidated in the current study." (PMID 37242182, 2023). "However, despite the uncovered link between food intake and the risks of insomnia associated with the CLOCK gene, no study has examined the impact of food groups on the association between the CLOCK gene and insomnia risks in the general population." (PMID 37242182, 2023).
leukemia (11 papers, 2019 to 2025). A malignant (clonal) hematologic disorder, involving hematopoietic stem cells and characterized by the presence of primitive or atypical myeloid or lymphoid cells in the bone marrow and the blood. "Furthermore, not only was CLOCK observed to have altered regulation in leukemias, but its analogue, the NPAS2 gene, was also found to be overexpressed in AML." (PMID 40700255, 2025). "In response to stimulation with IL20 in vitro, we also observed a pronounced cycling activity of CLOCK-transduced leukemia T-cells, as well as decrease of the fraction of cells at the early apoptotic stage, confirming that CLOCK-overexpressing cells are more responsive to IL20 treatment." (PMID 37620852, 2023). "As for BMAL1 and CLOCK genes, both were shown to be downregulated in all types of leukemia." (PMID 35897788, 2022). "In another recent study, it was shown that the circadian rhythm transcription factors BMAL1 and CLOCK were demonstrated to be essential for the formation of leukemia stem cells in acute myeloid leukemia (AML), and disruption of circadian pathway components might cause anti-leukemic effects." (PMID 38892035, 2024). "One study found that both CLOCK and BMAL1 proteins are required for leukemia stem cell growth, and disruption of the circadian clock leads to LSC differentiation, thereby inhibiting progression." (PMID 38334474, 2024). "PER1/2/3, BMAL1, CLOCK, REV-ERBα, and PPARα were downregulated in all types of leukemia, suggesting their potential role in leukemic development." (PMID 35897788, 2022). "CLOCK and BMAL1 are required for acute myeloid leukaemia cell growth and leukaemia stem cell maintenance." (PMID 31014368, 2019). "On the basis of previous evidence that, differently from healthy hematopoietic cells, the leukemia stem cells fully rely on a properly functioning molecular clockwork for survival and growth, we evaluated the role of the core circadian transcription factors BMAL1 and CLOCK in T-ALL biology." (PMID 37620852, 2023). "Therefore, the down-regulation of CLOCK and BMAL1 could be used as a biomarker in leukemia to support the identification of the disease; thus, the elevation of its expression compared to normal levels can be used to follow the response to treatments." (PMID 35897788, 2022).